NHLRC1 (NHL repeat containing E3 ubiquitin protein ligase 1)
Description:
E3 ubiquitin-protein ligase. Together with the phosphatase EPM2A/laforin, appears to be involved in the clearance of toxic polyglucosan and protein aggregates via multiple pathways. In complex with EPM2A/laforin and HSP70, suppresses the cellular toxicity of misfolded proteins by promoting their degradation through the ubiquitin-proteasome system (UPS). Ubiquitinates the glycogen-targeting protein phosphatase subunits PPP1R3C/PTG and PPP1R3D in a laforin-dependent manner and targets them for proteasome-dependent degradation, thus decreasing glycogen accumulation. Polyubiquitinates EPM2A/laforin and ubiquitinates AGL and targets them for proteasome-dependent degradation. Also promotes proteasome-independent protein degradation through the macroautophagy pathway.
Synonyms: EPM2B; bA204B7.2; MALIN; MELF2
Tractability: No criterion of Open Targets' tractability assessment is met for any kind of drug.
Gene: Protein-coding gene on chromosome 6 (18,120,440 to 18,122,677, reverse strand). Ensembl gene ENSG00000187566.
Subcellular location: Endoplasmic reticulum; Nucleus
Subcellular location (Human Protein Atlas): Nucleoplasm; Cytosol
Pathways (Reactome):
Disease: Myoclonic epilepsy of Lafora
Metabolism: Glycogen synthesis
Gene Ontology:
Molecular function: protein binding; ubiquitin protein ligase activity; ubiquitin-protein transferase activity
Biological process: proteasome-mediated ubiquitin-dependent protein catabolic process; protein polyubiquitination; ubiquitin-dependent protein catabolic process; glycogen biosynthetic process; protein ubiquitination
Cellular component: nucleoplasm; nucleus; cytosol; cytoplasm; endoplasmic reticulum; perinuclear region of cytoplasm
Genetic constraint (gnomAD): Loss-of-function variants: 12 observed, 17.17 expected, observed/expected ratio (o/e) 0.7, 90% interval 0.45 to 1.13. The upper end of that interval is the gene's LOEUF score, 1.13, which puts it in group 4 of 6, group 1 being the genes least tolerant of losing a copy. Missense variants: 526 observed, 521.13 expected, observed/expected ratio (o/e) 1.01, 90% interval 0.94 to 1.09. Synonymous variants: 231 observed, 223 expected, observed/expected ratio (o/e) 1.04, 90% interval 0.93 to 1.15.
Gene-disease validity (ClinGen):
ClinGen rates the evidence that NHLRC1 causes each of these diseases.
Lafora disease (autosomal recessive): Definitive. Lafora disease (LD) is a rare, inherited, severe, progressive myoclonic epilepsy characterized by myoclonus and/or generalized seizures, visual hallucinations (partial occipital seizures), and progressive neurological decline.
Homologues: Orthologues: chimpanzee NHLRC1 (100% identical), macaque NHLRC1 (98% identical), dog NHLRC1 (87% identical), rat Nhlrc1 (84% identical), rabbit NHLRC1 (83% identical), mouse Nhlrc1 (82% identical), guinea pig NHLRC1 (62% identical), tropical clawed frog nhlrc1 (45% identical).
Diseases named in the same sentence as NHLRC1 in open-access papers:
NHLRC1 is named in the same sentence as 41 diseases in open-access papers, as found by Europe PMC text mining. Sharing a sentence is not in itself a finding about the gene and the disease. The quoted sentences say what the papers report.
Lafora disease (37 papers, 2011 to 2026). "In beagles, a repetitive sequence of 12 nucleotides in the NHL Repeat Containing E3 Ubiquitin Protein Ligase 1 (NHLRC1; EPM2B) gene, which has an autosomal recessive inheritance pattern, has been shown to cause Lafora disease." (PMID 38275603, 2024). "Lafora Disease has been reported in multiple dog breeds as an autosomal recessive trait caused by repeat expansion variation in NHLRC1 (EPM2B), with an average age of disease onset of 7 years." (PMID 37107612, 2023). "Lafora disease is a rare disorder caused by loss of function mutations in either the EPM2A or NHLRC1 gene." (PMID 36899857, 2023). "The results of genetic testing also confirmed the diagnosis of Lafora disease, by detecting a mutation on the NHLRC1 gene." (PMID 36192771, 2022). "Lafora disease in dogs is caused by a repeat expansion mutation in the NHL repeat containing the E3 ubiquitin protein ligase 1 (NHLRC1) gene." (PMID 34357061, 2021). "The genetic testing of this repeat in the Chihuahua, French Bulldog, Griffon Bruxellois and mixed-breed dog confirmed the presence of dodecamer repeat expansion mutation in NHLRC1 previously reported in several other breeds affected with Lafora disease." (PMID 34357061, 2021). "Genetic testing for the known canine NHLRC1 mutation confirmed the presence of a homozygous mutation associated with canine Lafora disease." (PMID 34357061, 2021). "Genetic testing revealed the diagnosis of Lafora disease due to a homozygous mutation in NHLRC1 (c.G436A, p.D146N, NM_198586) whereas skin biopsy was unremarkable." (PMID 31551911, 2019). "The prevalence of IVDD in MWHDs in 17.7% which is significantly higher than the frequency of 7.1% of homozygous NHLRC1 mutation associated with Lafora disease presented here." (PMID 29610669, 2018). "Lafora disease in dogs is caused by a repeat expansion mutation in the NHL repeat containing E3 ubiquitin protein ligase 1 (NHLRC1) gene, a gene known to cause Lafora disease in humans." (PMID 29610669, 2018). "Within the tested dogs 7.0% (51/733) were homozygous for the NHLRC1 dodecamer repeat expansion mutation associated with canine Lafora disease." (PMID 29610669, 2018). "Consequently, the child was referred to an advanced center for genetic testing, which also confirmed diagnosis of Lafora disease with a positive mutation on NHLRC1 gene." (PMID 36192771, 2022). "So far, Lafora disease due to NHLRC1 dodecamer repeat expansion mutation has been reported in Miniature Wirehaired Dachshund, Basset Hound, Beagle, Chihuahua, Pembroke Corgi and the following breeds on the basis of histology: Miniature Poodle, Standard Poodle and Pointer." (PMID 34357061, 2021). "For example, an adult-onset Lafora disease patient was reported to exhibit bradykinesia, rigidity, and dopaminergic deficits based on DAT imaging, while a teenage patient carrying an NHLRC1 mutation presented with early parkinsonian symptoms." (PMID 41348744, 2025). "Expression levels of miRNAs linked to NHLRC1 and EPM2A genes (miR‐326 for NHLRC1 and miR‐383‐5p for EPM2A), key to Lafora Disease (LD) pathogenesis, were evaluated." (PMID 40542608, 2025). "Lafora disease (LD), a fatal neurodegenerative disorder, is caused by mutations in the EPM2A gene encoding laforin phosphatase or NHLRC1 gene encoding malin ubiquitin ligase." (PMID 39301689, 2024). "We identified the homozygous variant c.137G>A, p.(Cys46Tyr), in the EPM2B/NHLRC1 gene, confirming the diagnosis of Lafora disease." (PMID 38137127, 2023). "Lafora disease is caused by loss-of-function mutations in the EPM2A gene, coding for a protein phosphatase (laforin), or of the NHLRC1 gene, coding for an E3 ubiquitin ligase (malin)." (PMID 38033781, 2023). "NHLRC1 was previously functionally characterized only in Lafora disease, a neurodegenerative type of myoclonus epilepsy." (PMID 36142605, 2022).
Lafora disease (continued). "Lafora disease can be caused by defects in the EPM2A gene, which encodes the laforin protein phosphatase, or in the NHLRC1 gene (also called EPM2B) codifying the malin E3 ubiquitin ligase." (PMID 24472629, 2014). "Loss of function mutations in NHLRC1 should thus impair cargo-targeting for autophagy in Lafora disease, but direct evidence of this has not been established." (PMID 41277110, 2026). "A multicenter study of 28 beagles diagnosed with Lafora disease included one dog that, despite only being heterozygous for the defect in the NHLRC1 gene, showed typical signs of the disease, contrary to what would be expected given the assumed autosomal recessive inheritance." (PMID 38275603, 2024). "A repeat expansion in the dog Nhlrc1 gene, the cause of its Lafora disease, does not appear to be present in humans, albeit non-repeat mutations in the same gene cause the same Lafora disease in humans." (PMID 36468036, 2022).
epilepsy (8 papers, 2011 to 2025). A brain disorder characterized by episodes of abnormally increased neuronal discharge resulting in transient episodes of sensory or motor neurological dysfunction, or psychic dysfunction. "The boy herein presented will be followed up for any reduction in his developmental delay or, on the other hand, any deterioration and/or newly presenting clinical symptoms or signs, such as seizures, since the missing NHLRC1 gene is associated with rapid and progressive adolescent-onset epilepsy." (PMID 34303382, 2021). "In the present era, patients with LD are diagnosed comparatively swiftly because EPM2A and NHLRC1 are included in most epilepsy gene panels, and therefore, most new patients would benefit." (PMID 33277363, 2021).
developmental delay (2 papers, 2012 to 2021). "The deletion found in the SCAP patient harbors ATXN1, DTNBP1, JARID2, and NHLRC1 that we propose may be responsible for ASDs and developmental delay." (PMID 22480366, 2012).
glycogen storage disease (2 papers, 2021 to 2022). "Polyglucosan body disease (PBD) is a type of glycogen storage disease (GSD) and is mainly caused by mutations in eight different human genes, namely, GYG1, GBE1, RBCK1, PFKM, EPM2A, EPM2B (NHLRC1), PRDM8, and PRKAG2." (PMID 33413275, 2021).
lung carcinoma (2 papers, 2021 to 2022). "In functional assays, we demonstrate attenuated proliferation, viability, migration, and invasion upon NHLRC1 knock-down in lung cancer cells." (PMID 36142605, 2022). "NHLRC1 holds promise as a new prognostic biomarker for lung cancer survival and prognosis, as well as a target for novel treatment strategies in lung cancer patients." (PMID 36142605, 2022). "To address functional roles of these DMRs in lung tumorigenesis we performed in depth in vitro characterization in lung cancer cell lines and report here on a novel gene, NHLRC1, involved in AKT activation." (PMID 36142605, 2022). "In line with this, we observed higher levels of NHLRC1 expression induced upon demethylation in DAC-treated BEAS 2B cells compared to lung cancer cell lines." (PMID 36142605, 2022). "To assess the regulatory potential of the identified DMR in NHLRC1, we analysed ChIP-seq data of activating and repressive histone marks from the Encyclopaedia of DNA Elements (ENCODE) project from the lung cancer cell line A549 and the normal lung fibroblast cell line NHLF." (PMID 36142605, 2022). "In addition, NHLRC1 KD attenuated transwell lung cancer cell migration and basement membrane invasion." (PMID 36142605, 2022). "Importantly, we observed that four of the five genes (STAG3, PODXL2, NHLRC1, and ZCWPW1) identified from our analysis in lung cancer models were significantly upregulated upon loss of MGA." (PMID 34236315, 2021).
Myoclonus (2 papers, 2022 to 2025). Very brief, involuntary random muscular contractions occurring at rest, in response to sensory stimuli, or accompanying voluntary movements. "Intragenic deletions and duplications can be found in the EPM2A and NHLRC1 (EPM2) genes, ASAH1 gene (SMA-PME), NUS1, and SGCE (myoclonus-dystonia)." (PMID 40584247, 2025).
myoclonus epilepsy (2 papers, 2022 to 2023). "Lafora disease is a progressive fatal autosomal recessive form of myoclonus epilepsy, caused by loss-of-function mutations of EPM2A or NHLRC1 genes, encoding the glycogen phosphatase laforin and the E3 ubiquitin ligase malin, respectively." (PMID 36935052, 2023).
Ataxia (1 paper, 2017). Ataxia refers to impaired coordination of voluntary muscle movement. "We also found three other genes that are differentially expressed due to Fxn knockdown, namely, CSTB, NHLRC1 and PMM2 all of which are associated with other disorders manifesting ataxia." (PMID 29257745, 2017).
atrial fibrillation (1 paper, 2023). A disorder characterized by an electrocardiographic finding of a supraventricular arrhythmia characterized by the replacement of consistent P waves by rapid oscillations or fibrillatory waves that vary in size, shape and timing and are accompanied by an irregular ventricular response. "SNPs located near the neighboring genes TPMT and NHLRC1 were associated with decreased risk of atrial fibrillation, autoimmune and inflammatory diseases, and increased risk of sleep disorders." (PMID 37076473, 2023).
diabetes mellitus (1 paper, 2019). A metabolic disorder characterized by abnormally high blood sugar levels due to diminished production of insulin or insulin resistance/desensitization. "Herein, we describe a 13-years-old child with LD due to a NHLRC1 (c.386C > A, p.Pro129His) mutation, who has developed diabetes mellitus and was treated with metformin." (PMID 30701169, 2019).
head and neck cancer (1 paper, 2024). A primary or metastatic malignant neoplasm affecting the head and neck. "The second highest cdNS values (cdNS = 7.312) was noted for NHLRC1 mutation contexts for FAT1 truncating mutations in head and neck cancers." (PMID 39160568, 2024).
liver fibrosis (1 paper, 2024). "Among these 47 SDE-identified genes, NCAPG and NHLRC1 were those that best at discriminating patients who achieved regression of liver fibrosis (LSMred>50%)." (PMID 39911830, 2024).
myoclonic epilepsy of (1 paper, 2025). "Our study illustrates the clinical heterogeneity and variable expression of the NHLRC1 variant p.Arg265Ter underlying myoclonic epilepsy of Lafora-2." (PMID 40217338, 2025).
neuroendocrine tumor (1 paper, 2023). "It has been reported that NHLRC1, an E3 ubiquitin protein ligase, mediates NNAT ubiquitination in PC12 neuroendocrine tumor cells." (PMID 36708951, 2023).
neurodegenerative disease (3 papers, 2019 to 2025). A disorder of the central nervous system characterized by gradual and progressive loss of neural tissue and neurologic function. "Lafora progressive myoclonus epilepsy (Lafora disease) is a rare, usually childhood-onset, fatal neurodegenerative disease caused by biallelic mutations in EPM2A (Laforin) or EPM2B (NHLRC1; Malin)." (PMID 32587944, 2019). "Canine Lafora disease is a recessively inherited, rapidly progressing neurodegenerative disease caused by the accumulation of abnormally constructed insoluble glycogen Lafora bodies in the brain and other tissues due to the loss of NHL repeat containing E3 ubiquitin protein ligase 1 (NHLRC1)." (PMID 34357061, 2021).
tumor (3 papers, 2019 to 2022). "In brief, the overexpression of NHLRC1 in tumor cells is associated with higher proliferation rates with an increased ability for migration and invasion, which is characteristic for cancer cells." (PMID 36142605, 2022). "This indicated that altered epigenetic regulation might be the cause for elevated NHLRC1 transcription in tumor tissue." (PMID 36142605, 2022). "Differential methylation at cg06646708 was of particular interest, since its hypomethylation was associated with overexpression of the closest gene, the ubiquitin E3 ligase NHLRC1 not only in lung tumors, but TCGA data from different tumor sites." (PMID 36142605, 2022). "Since NHLRC1 was overexpressed in tumor tissue, we aimed to characterize NHLRC1 functions in more detail." (PMID 36142605, 2022). "By analysing an independent sample set of tumor versus adjacent normal (Replication Set II), we confirmed the NHLRC1 DMR hypomethylation." (PMID 36142605, 2022). "CST2 expression differed only between LUAD and non-tumor tissues, and NHLRC1 expression differed between LUSC and non-tumor tissues." (PMID 35399076, 2022). "In addition, we analyzed the gene expression profile of GSE85841 that included eight LUAD samples and adjacent non-tumor samples with adjusted P < 0.05 and logFC≥1.5, and researched the top five most significantly upregulated genes: SFRP5, CST2, SPP1, GCNT3, and NHLRC1." (PMID 35399076, 2022).
cancer (2 papers, 2019 to 2022). A tumor composed of atypical neoplastic, often pleomorphic cells that invade other tissues. "Our results also show that ETS1 is degraded by the NHLRC1-induced ubiquitination in early stage to allow cancer cells to maintain in early stage by inhibiting invasive functions, such as cell migration and ECM remodeling." (PMID 31217907, 2019).
genetic disorder (1 paper, 2024). "Lafora disease (LD) is an autosomal recessive genetic disorder produced by a mutation of NHLRC1 or EPM2B genes that encodes malin and laforin glycogen phosphatase." (PMID 39511714, 2024).
NHLRC1 also shares sentences with these, for which no sentence is quoted: progressive myoclonus epilepsy (7 papers); Progressive myoclonic epilepsy (3); Anxiety (2); dementia (2); neurologic disorder (2); ceroid lipofuscinoses (1); cognitive decline (1); deafness (1); Dyskinesia (1); Dystonia (1); lactic acidosis (1); lung adenocarcinoma (1); lung squamous cell carcinoma (1); MELAS (1); memory impairment (1); metabolic syndrome (1); Obesity (1); Onset (1); panic attacks (1); sleep disorder (1); squamous cell carcinoma (1); steatosis (1); tonic-clonic seizures (1).